GAPDH (glyceraldehyde-3-phosphate dehydrogenase)
Diseases named in the same sentence as GAPDH in open-access papers (continued):
Sharing a sentence is not in itself a finding about the gene and the disease.
Hyperglycemia (continued). "Hyperglycaemia has also been shown to induce excessive superoxide production by the ETC, causing oxidative stress in aortic endothelial cells, and inducing a decrease in GAPDH activity." (PMID 38736550, 2024). "The feed-back impact of hyperglycaemia on glucose sensitive elements in this gene might explain why GAPDH is less stable in diabetic environments." (PMID 36627346, 2023). "In addition, hyperglycaemia (or diabetes) dramatically inhibits GAPDH activity, thereby impairing glucose metabolism." (PMID 36376280, 2022). "Overactivated FoxO1 can also promote the expression of inducible NO synthase in DCM, and further induce the nitrosylation of target proteins such as glyceraldehyde-3-phosphate dehydrogenase and caspase-3, leading to post-hyperglycemia myocardial cell death and myocardial dysfunction." (PMID 36147338, 2022). "Hyperglycemia also diminishes the activity of the key glycolytic enzyme glyceraldehyde-3 phosphate dehydrogenase (GAPDH), and afterward, the level of all the glycolytic intermediates that are upstream of GAPDH increases." (PMID 33123598, 2020). "Aside from ROS generated through mitochondrial failure, hyperglycemia may trigger the onset of oxidative stress via pathways that dwell upstream the glycolytic enzyme GAPDH." (PMID 31787891, 2019). "The buildup of fructose, both upstream GAPDH as well as a product of the polyol pathway, may represent a further mediator of the neuronal damage induced by hyperglycemia." (PMID 31787891, 2019). "Moreover, hyperglycemia stimulates GAPDH accumulation in the nucleus of retinal Müller cells, in association with the apoptosis of these cells." (PMID 30475883, 2018). "Moreover, decreased NADPH levels lead to the inhibition of GAPDH, which in turn activate four hyperglycemia-induced pathways." (PMID 26881021, 2016). "Notably a key gluconeogenic enzyme glucose-6-phosphatase is up regulated in livers of HYP-mice resulting in hyperglycemia and as discussed our studies show down regulation of GAPDH a key glycolytic enzyme." (PMID 24839967, 2014). "In contrast to other metabolic enzymes, such as GAPDH, whose activity is SUMOylation-dependant, the increased activity of MDH2 following SUMOylation is likely to maintain ETS functionality and energy supply and thereby help to overcome cellular stress and damage caused by hyperglycaemia." (PMID 37947589, 2023). "Acute and chronic hyperglycaemia regulated PDHe1α phosphorylation in LG-cells and HG-cells in a similar manner to that observed in control and diabetic islets; and chronic GAPDH inhibition in LG-cells recapitulated the effect of chronic hyperglycaemia on PDHe1α phosphorylation." (PMID 36376280, 2022). "In addition, hyperglycemia induces mitochondrial superoxide production which in turn activates four damaging pathways in cells through inhibiting the activity of the key glycolytic enzyme glyceraldehyde-3-phosphate dehydrogenase." (PMID 26317017, 2013). "It has been reported that chronic hyperglycemia can lead to an inhibition of pyruvate dehydrogenase (PDH) through mTOR-S6 signaling, which is triggered by glycolytic metabolites upstream of glyceraldehyde-3-phosphate dehydrogenase (GAPDH)." (PMID 40738954, 2025). "We also report that expression of GAPDH and PPIB in PBMCs is affected by hyperglycaemia in T2DM patients making them unsuitable as references genes for measuring mRNA expression." (PMID 36627346, 2023). "Hyperglycemia inhibits glyceraldehyde-3-phosphate dehydrogenase (GAPDH) activity and slows down glycolysis as a result of poly(ADP-ribosyl)ation of GAPDH by PARP." (PMID 38264279, 2023). "Together, these data suggest that chronic hyperglycaemia leads to PDH inhibition via mTORC1 signalling, and that this pathway is triggered via a glycolytic metabolite upstream of GAPDH." (PMID 36376280, 2022).
Hyperglycemia (continued). "What’s more, GAPDH inhibition was found to be a consequence of poly (ADP ribosyl) ation of GAPDH by PARP, which was activated by DNA strand breaks produced by reactive species generated by hyperglycemia." (PMID 33838689, 2021). "Inhibition of calpain also restored the levels of autophagy in both iPSC-ECs and HAECs exposed to hyperglycemia marked by higher levels of BECLIN 1 and LC3-II normalized against GAPDH and increased formation of autophagosomes." (PMID 30799273, 2019). "Moreover, a reduction in GAPDH activity is considered a converging point of multiple deleterious pathways activated by hyperglycemia and a key step in the pathogenesis of DM complications; therefore, the ability of HSPB1 to activate GAPDH may be particularly advantageous in DM." (PMID 29240668, 2017). "SPR4 increased GAPDH HYP-bone expression 60× and corrected HYP-mice hyperglycemia and hypoinsulinemia." (PMID 24839967, 2014). "RONS produced during hyperglycemia induce breaks in nuclear DNA and activate PARP expression, which modifies glyceraldehyde-3-phosphate dehydrogenase (GAPDH) and decreases its activity, thus fostering complication pathways of diabetes." (PMID 23385234, 2013). "Hyperglycaemia increases the availability of the glycolytic intermediate glyceraldehyde-3-phosphate (GAP), a DAG precursor, due to the inhibition of the glycolytic enzyme glyceraldehyde-3-phosphate dehydrogenase (GAPDH) by the PARylation process." (PMID 40243689, 2025). "In addition, hyperglycemia-induced ROS production activates poly (ADP-ribose) polymerase, which inhibits glyceraldehyde-3-phosphate dehydrogenase (GAPDH)." (PMID 40722979, 2025). "Hyperglycemia provokes overproduction of ROS and DNA single-strand cracks, both of which can stimulate PARP, thereby resulting in an alteration of GAPDH and a decrease of its activity." (PMID 33123598, 2020). "In contrast, hyperglycemia could lead to increased alkaline phosphatase expression and suppressed Osteocalcin, MMP-13, VEGF, and GAPDH levels in osteoblasts resulting in osteoporosis." (PMID 25742620, 2015). "In summary, hyperglycemia induces mitochondrial generation of ROS, activates PARP, and reduces GAPDH activity, which in turn contributes to increased flux of the polyol pathway, activates PKC, increases intracellular production of AGEs, and overactivates the hexosamine pathway." (PMID 25180070, 2014). "Also, SPR4 increased GAPDH bone expression 60× fold and corrected HYP-mice hyperglycemia and hypoinsulinemia." (PMID 24839967, 2014). "The inhibition of GAPDH activity by “hyperglycemia” does not occur when mitochondrial overproduction of superoxide is prevented by either UCP1 or MnSOD." (PMID 22253615, 2012). "In the vascular endothelium, hyperglycemia induces overproduction of O2•− by the mitochondrial ETC and reduces the activity of the key glycolytic enzyme glyceraldehyde-3 phosphate dehydrogenase (GAPDH) leading to the activation of three major pathways of hyperglycemic damage." (PMID 25143800, 2014). "Thus, it consequently decreases the activity of GAPDH, increasing the flow of the polyol pathway, stimulates PKC, increases the production of AGEs within cells, and excites the hexosamine pathway, establishing a close relationship between hyperglycemia and oxidative stress." (PMID 35052633, 2022). "In our hyperglycemia-induced, no-treatment control group, we used real-time PCR to show a signaling pathway consistent with that of CTB cells subjected to glucose insult, including downregulation of the mRNA expression of uPA/GAPDH and PA-1/GAPDH." (PMID 39329718, 2024).
Alzheimer disease (46 papers, 2011 to 2025). A progressive, neurodegenerative disease characterized by loss of function and death of nerve cells in several areas of the brain leading to loss of cognitive function such as memory and language. "GAPDH has been implicated in diseases such as Alzheimer’s disease (AD) and other neurodegenerative disorders In AD, post-translationally modified GAPDH accumulates in the brain, contributing to amyloid-β amyloidogenesis." (PMID 41006687, 2025). "Recent research also demonstrated that the S-nitrosylation of GAPDH substantially contributes to the increased tau acetylation during Alzheimer's disease (AD) pathogenesis linked with traumatic brain injury (TBI)." (PMID 38493183, 2024). "Aberrant GAPDH function has been associated with different neurodegenerative pathologies, including Alzheimer’s disease (AD), Parkinson’s disease (PD) and Huntington’s disease (HD)." (PMID 33339386, 2020). "Human diseases (e.g., Alzheimer’s disease—Section 5) are associated with the aggregation of GAPDH due to the formation of intermolecular disulfides." (PMID 33339386, 2020). "Of note, nitrosylation of GAPDH can also augment tau acetylation in the presence of Abeta1-42, which causes a violation in the microtubule association process and the amount of nitrosylated GAPDH is increased in post-mortem Alzheimer’s disease (AD) brains." (PMID 32370188, 2020). "On the basis of these results, it can be concluded that isoeugenol from Ocimum tenuiflorum could be taken for further in vitro and in vivo analysis, targeting GAPDH inhibition for the amelioration of diabetes mellitus-linked Alzheimer’s disease." (PMID 35458596, 2022). "It was shown that extracellular complexes of GAPDH and beta-amyloid peptide exhibit high cytotoxicity, and may be one of the causes of neurodegenerative changes in Alzheimer’s disease." (PMID 34827652, 2021). "Importantly, single nucleotide polymorphisms in the GAPDH gene have been associated with late onset Alzheimer's disease." (PMID 26619001, 2015). "The pathways related to neurodegenerative disease, such as Alzheimer’s disease and Huntington’s disease, were also enriched with two essential DEPs (GAPDH, PLCB3 and SP1, PLCB3, respectively)." (PMID 35741576, 2022). "GAPDH is S-glutathionylated, which results in the amyloid build-up and, ultimately, Alzheimer’s disease (AD)." (PMID 36290644, 2022). "Recently, a high correlation of S−glutathionylated GAPDH in the blood correlated with the progression of Alzheimer’s Disease (AD), and GAPDH was identified as one of four hub genes associated with AD in a gene profiling study." (PMID 35562998, 2022). "The ACE2/GAPDH ratio values obtained from 13 patients with Alzheimer’s disease ranged from 0.3 to 3 (mean = 1.2 ± 0.2), while those of control subjects were highly consistent with a mean of 0.26 ± 0.04." (PMID 33567524, 2021). "It is likely that the same pathway involving the S-nitrosylation of GAPDH and SirT1 leads to the stimulation of the acetylation of the tau protein involved in the development of Alzheimer’s disease." (PMID 34827652, 2021). "The carbonyl content-to-GAPDH ratio values ranged from 0.7 to 2.9 (mean = 1.4 ± 0.15) in brains with Alzheimer’s disease, while those of controls had a range of 0.1 to 0.2 (mean = 0.2 ± 0.02)." (PMID 33567524, 2021). "In a similar study, exosomes carrying the siRNAs of glyceraldehyde-3-phosphate dehydrogenase (GAPDH; the housekeeping gene) or β-site APP cleaving enzyme -1 (BACE1; an Alzheimer’s disease-associated gene) downregulated targeted protein level in neurons." (PMID 33800282, 2021). "Consistently, it is believed that inactivated, aggregation-prone GAPDH can enhance such pathologies as Alzheimer’s disease, Huntington’s disease, Parkinson’s disease, diabetes, secondary damage after traumatic brain injury and many others." (PMID 32370188, 2020).
Alzheimer disease (continued). "Regarding the mechanism, an increasing amount of research demonstrates that GAPDH tends to translocate into the nuclei of neurons in several neurodegenerative disorders, such as Huntington disease, Alzheimer’s disease and stroke." (PMID 29390963, 2018). "Intriguingly, recent studies indicate that GAPDH is involved in the pathogenesis of several neurodegenerative conditions such as Alzheimer’s disease (AD) and PD." (PMID 26258539, 2015). "In Alzheimer disease, both GAPDH expression and nitrosylation are increased, probably leading to elevated concentrations of GAPDH-Siah in the nucleus, which in turn promotes apoptosis." (PMID 22028962, 2012). "It has been shown that the expression of GAPDH was decreased by antioxidant treatments in aged neural cells from Alzheimer's disease patients." (PMID 22194971, 2011). "Mutation or reduced expression or activity of glycolytic enzymes including hexokinase (HK), glyceraldehyde-3-phosphate dehydrogenase (GAPDH), and phosphoglycerate kinase (PGK) have been linked to neurodegenerative diseases such as retinitis pigmentosa, Alzheimer's disease, and ALS, respectively." (PMID 40505722, 2025). "Moreover, in Alzheimer’s disease, S-glutathionylation of glyceraldehyde 3-phosphate dehydrogenase (GAPDH) prevents the correct functioning of this protein involved in the glycolytic pathway." (PMID 38001829, 2023). "Thus, it was shown that the hydrocortisone derivative RX624, capable of binding GAPDH, in a 5xFAD transgenic mice model of Alzheimer’s disease, not only inhibited the formation of the GAPDH–Aβ complex, but also prevented memory impairment." (PMID 37259455, 2023). "Notably, studies have demonstrated that there is a significant inhibition of GAPDH activity in the Alzheimer’s disease brain." (PMID 36450447, 2023). "Thus, compounds that prevent the participation of GAPDH in aggregation processes in Huntington’s disease, such as deprenyl, and in oxidative stress accompanying Alzheimer’s disease, such as GAI, have been proposed as neuroprotective agents." (PMID 36678636, 2022). "GAPDH is a key gene in sugar metabolism, but a large number of independent studies have shown that GAPDH has non-glycolytic activity and is involved in pathogenesis and death in neurodegenerative diseases, such as Alzheimer's disease and Parkinson's disease." (PMID 34108502, 2021). "GAPDH may play a role in the neurodegenerative disorders such as Alzheimer’s disease and Huntington’s disease and might participate in both proapoptotic and oncogenic processes." (PMID 34249897, 2021). "GAPDH aggregation is observed in diseases such as Alzheimer’s disease (Section 5)." (PMID 33339386, 2020). "Besides cancer, the functional versatility of this enzyme determines that GAPDH alteration is involved in several other diseases especially neurodegenerative disorders such as Alzheimer’s disease (AD), Parkinson’s disease (PD) and Huntington’s disease (HD)." (PMID 31027346, 2019). "The NO/GAPDH/Siah1 signaling cascade may also be conducive to further understand the molecular mechanism of GAPDH in neurodegenerative disorders (e.g., Alzheimer’s disease and Parkinson’s disease)." (PMID 30845728, 2019). "Aggregated GAPDH in the brain is also amyloidogenic, and GAPDH amyloidal aggregates colocalize with Lewy bodies in Parkinson's disease and with senile plaques and neurofibrillary tangles in Alzheimer's disease (20, –, 23)." (PMID 28167533, 2017). "In addition, GAPDH enhances aggregation and cytotoxicity in models of Huntington and Amytrophic Lateral Sclerosis as well as Alzheimer’s disease." (PMID 26465331, 2015). "As Alzheimer's disease is characterized by the collapse of proteostasis and GAPDH is involved, discovering novel stabilizing components could provide therapeutic targets for further research." (PMID 26619001, 2015). "Moreover, the oxidant-induced changes in GAPDH subcellular localization probably play a role in the pathology of Alzheimer disease." (PMID 22028962, 2012).
Alzheimer disease (continued). "The institutional review board (IRB) at each participating centre (Taipei Veterans General Hospital IRB (IRB No. 2013-04-044B) and Taiwan Adventist Hospital IRB (IRB No. 108-E-10)) approved the study protocol used to investigate whether blood GAPDH could be a biomarker of Alzheimer’s disease." (PMID 32469899, 2020). "In addition, relative GAPDH mRNA expression levels in peripheral blood mononuclear cells from healthy individuals of young age (chronicle age: 20s and 30s) and old age (chronicle age: > 50s), as well as patients with Alzheimer’s disease, were gradually downregulated with aging." (PMID 32938817, 2020). "Glyceraldehyde-3-phosphate dehydrogenase (GAPDH) is involved in energy production and has been shown to convert from its native soluble state into a non-native high molecular weight, which is insoluble, and an aggregated state, during the course of several diseases, including Alzheimer’s disease." (PMID 31405050, 2019). "GAPDH has been reported to contribute to neurological disorder such as Huntington and Alzheimer diseases which indicates GAPDH might not be an optimal candidate gene in hypothalamus." (PMID 28591185, 2017).